PTH (parathyroid hormone)
Diseases named in the same sentence as PTH in open-access papers (continued):
Sharing a sentence is not in itself a finding about the gene and the disease.
Hypercalcemia (continued). "Although further proof is needed to confirm this, for ice swimmers, who has hyperparathyroidemia, hypercalcemia, and hyperphosphatemia themselves, their blood PTH, Ca2+, and Pi levels should be regularly measured and/or they should consider avoid IS." (PMID 34899374, 2021). "Primary hyperparathyroidism (PHPT) is characterized by hypercalcemia and an elevated level of serum parathyroid hormone (PTH)." (PMID 33761720, 2021). "It is characterised by inappropriate and excessive secretion of parathyroid hormone (PTH) from one or more parathyroid glands resulting in hypercalcaemia." (PMID 34647901, 2021). "After surgery hypercalcemia persisted with calcium levels between 2.60 mmol/L and 2.65 mmol/L and PTH between 2.1 pmol/L and 3.6 pmol/L." (PMID 33544354, 2021). "Beside, IH patients present with hypercalcemia, low PTH, normal to high 1–25 OH vitamin D. Clinically, IH patients present low body mass index or failure to thrive, polyuria or dehydration, hypotonia and nephrocalcinosis at ultrasound analysis." (PMID 33952337, 2021). "The contraindications for PTH injection include patients sensitive to osteosarcoma, patients with Paget’s disease, pre-existing hypercalcemia, and history of other skeletal disorders." (PMID 34760881, 2021). "In this study, we describe the follow up of 10 pediatric patients who presented to our referral center with hypercalcemia, nephrocalcinosis, or nephrolithiasis, and with a typical biochemical profile of elevated 1,25-(OH)2D and suppressed PTH." (PMID 34858904, 2021). "Elevated levels of PTH lead to persistent hypercalcemia, which often presents with subtle clinical symptoms." (PMID 33761720, 2021). "Laboratory examinations revealed high serum concentrations of GH and PRL with mild hypercalcemia, hyperphosphatemia, hypercalciuria, inhibited PTH concentration, and increased bone turnover markers." (PMID 33933067, 2021). "An animal study claimed that continuous infusion of PTH in CKD rats led to the development of hypercalcemia and severe calcification of the aortal medial layer." (PMID 34408941, 2021). "Primary hyperparathyroidism (PHPT) is a common endocrine disease that is characterized by hypercalcemia and an elevated level of serum parathyroid hormone (PTH)." (PMID 33761720, 2021). "When she was 68 years’ old, her primary care doctor noted mild hypercalcemia and an increased level of intact parathyroid hormone (iPTH)." (PMID 33761720, 2021). "During his hospitalization, the patient was found to have hypercalcemia and elevated parathyroid hormone (PTH)." (PMID 34416869, 2021). "The most significant side-effect attributable to paricalcitol treatment was hypercalcaemia with significant suppression of PTH." (PMID 31830258, 2021). "They present with metaphyseal chondrodysplasia, hypercalcaemia, hypophosphatemia, undetectable serum levels of PTH and PTHrP, decreased renal tubular reabsorption of P and increased cAMP in urine." (PMID 34068220, 2021). "Primary hyperparathyroidism (PHPT) is a common endocrine disease and is defined as hypercalcemia with increased or inappropriately normal plasma parathyroid hormone (PTH)." (PMID 33827463, 2021). "Following surgery, intact PTH level elevation and hypercalcemia progression due to recurrent disease were noted." (PMID 33858470, 2021). "Blood tests for clarification of hypercalcemia, revealed suppressed parathyroid hormone (PTH 1.2 ng/l) and elevated calcitriol (147 ng/l), but normal levels of serum phosphate (1.12 mmol/l) and urinary calcium (4.46 mmol/l)." (PMID 33824685, 2021). "In the work-up for hypercalcemia, serum intact parathyroid hormone (PTH) level was elevated at 78.7 pg/mL, and recheck level was more increased up to 128 pg/mL (normal range, 15–65)." (PMID 33632163, 2021). "The vast majority of patients with PHPT harbour a single parathyroid adenoma (PA) whose secretion of parathyroid hormone (PTH) is incompletely inhibited by hypercalcaemia." (PMID 37435188, 2021).
Hypercalcemia (continued). "During the patient’s first endocrinological evaluation, hypercalcemia (2.7 mmol/L) and elevated PTH (230 pg/mL) were detected." (PMID 33807230, 2021). "According to previous studies, the potential mechanisms for high incidence of PTC in PHPT patients included shared embryological origin and genes and high level of PTH and 1,25-hydroxy vitamin D, as well as hypercalcemia." (PMID 34158812, 2021). "Her laboratory test results revealed a high parathyroid hormone level (822 pg/ml) and hypercalcemia (2.52 mmol/L) in the blood." (PMID 33413306, 2021). "Patients with FHH present with mild to moderate hypercalcaemia, low urinary excretion, and PTH serum levels that are either normal or slightly elevated." (PMID 33544354, 2021). "As expected, the patient continued to have PTH-dependent hypercalcemia; however, unexpectedly, the target lesion persisted on follow up US and FCH-PET/CT." (PMID 33499837, 2021). "It is a rare autosomal-dominant disorder with very low urinary calcium excretion and mild hypercalcemia with high normal or slightly elevated PTH." (PMID 34736428, 2021). "Primary hyperthyroidism (PHPT) is a common endocrine disorder characterized by hypercalcemia and elevated or inappropriately normal parathyroid hormone (PTH) levels." (PMID 33413316, 2021). "Hypercalcemia of malignancy usually has higher serum calcium levels equal to or greater than 13 mg/dl and PTH levels are usually suppressed." (PMID 34462682, 2021). "Primary hyperparathyroidism (PHPT) is a common endocrine disease characterized by persistent elevated levels of parathyroid hormone (PTH), leading to hypercalcemia." (PMID 34440663, 2021). "Sustained hypercalcemia can reduce glomerular filtration rate, suppress PTH, impair creatinine clearance, and ultimately lead to renal insufficiency." (PMID 33732556, 2021). "Exogenous vitamin D toxicity is defined by very increased 25(OH)D levels (>150 ng/mL), severe hypercalcemia and hypercalciuria, and extremely low or undetectable parathyroid hormone (PTH) activity." (PMID 34944659, 2021). "Paricalcitol, a synthetic analog of vitamin D, less hypercalcemia and hypercalcemia, effectively decreases PTH, particularly administrated intravenously compared to the Calcitriol." (PMID 34368073, 2021). "Elevated PTH can stimulate cardiac myocyte hypertrophy, dysfunction of endothelium and vasculature, and hypercalcemia and activate aldosterone via RAAS." (PMID 34222377, 2021). "Parathyroid adenomas are benign, parenchymal tumors that often secrete parathyroid hormone (PTH), causing hypercalcemia." (PMID 34421830, 2021). "Hypercalcemia with an elevated parathyroid hormone (PTH) level seen in recurrent and metastasis disease cases is often refractory to medical therapy, thus surgical resection is recommended when possible." (PMID 33858470, 2021). "FHH describes a condition of PTH-dependent hypercalcemia, resembling and in the differential diagnosis of HPT, that is typically benign." (PMID 33716975, 2021). "After initial treatment of the metastasis with surgery and irradiation, he developed a relapse with severe hypercalcemia and corresponding elevated parathyroid hormone levels." (PMID 33413267, 2021). "Primary hyperparathyroidism (PHPT) and familial hypocalciuric hypercalcemia (FHH) are the most important differential diagnosis of parathyroid hormone (PTH)-dependent hypercalcemia." (PMID 34736428, 2021). "Abnormal levels are illustrated using 4 thresholds for elevated PTH, 2 each for elevated phosphorus and ALP, 2 for 25D (deficiency and insufficiency), and 2 for calcium (hypo- and hypercalcemia)." (PMID 33912763, 2021). "A 29-year old woman was initially evaluated for PTH-dependent hypercalcemia in 2013 when she was 22 years old." (PMID 33499837, 2021). "Workup for his hypercalcemia revealed a normal intact parathyroid hormone (PTH) level of 20 pg/mL (Ref: 15–65 pg/mL), though repeat PTH following zoledronic acid infusion was low at 10 pg/mL (Ref: 15–65 pg/mL)." (PMID 34258083, 2021).
Hypercalcemia (continued). "Of these, hypophosphatasia caused by loss-of-function TNSALP mutations, in its severest forms (perinatal and infantile) can present with profound skeletal hypomineralisation and bone deformity, hypercalcaemia with downregulation of PTH, and hypercalciuria." (PMID 33614549, 2021). "Biochemical evaluation showed hypercalcemia (2,85 mmol/L; normal: 2.15–2.55 mmol/L) with slightly lowered PTH levels (14,2 ng/L; normal 14,9–56,9 ng/L) excluding hyperparathyroidism." (PMID 33008295, 2020). "The study of phosphocalcic metabolism, requested in this context, showed a severe PTH‐dependent hypercalcemia, with a serum albumin‐adjusted total calcium of 4.39 mmol/L (normal range, 2.09‐2.42 mmol/L) and PTH of 3000 pg/mL (normal range 15‐65 pg/mL)." (PMID 32884778, 2020). "Tertiary hyperparathyroidism (HPT) is a metabolic disorder characterized by the semi-autonomous hypersecretion of parathyroid hormone (PTH), leading to hypercalcemia." (PMID 33092198, 2020). "Case presentation: We report the unusual case of a 53-year-old lady who presented with hypercalcaemia and elevated parathyroid hormone with a presumed diagnosis of primary hyperparathyroidism." (PMID 32613005, 2020). "In 2015, his laboratory investigations revealed hypercalcemia (2.83 mmol/L) and elevated serum PTH levels (380 pg/mL)." (PMID 33101196, 2020). "Same conclusions were observed with the IV administration of parathyroid or partially purified PTH-induced hypercalcemia, conforming its advantages in hypercalcemia." (PMID 32963524, 2020). "Overall the treatment lowered PTH levels, the exceptions being patients who started treatment in the context of hypercalcemia." (PMID 32075103, 2020). "From the current literature, it seems evident that the majority of PLA cases are female patients exhibiting classical features of PHPT, in which the excision often leads to the reversion of hypercalcemia and/or elevated PTH levels." (PMID 32193823, 2020). "Primary hyperparathyroidism is characterized by hypercalcemia and elevated or inappropriately normal serum levels of parathyroid hormone." (PMID 31931802, 2020). "The measured clearance of inulin was 100% higher in patients with hypercalcemia due to PHPT than in patients with PTH-independent hypercalcemia, controlling for the level of calcium." (PMID 33382714, 2020). "A woman in her seventies presented with hypercalcaemia (Ca = 2.80 mmol/l, 11.2 mg/dl) and hyperparathyroidism (PTH = 12.8 pmol/l), and her CCCR was elevated at 1.5% suggesting PHPT." (PMID 31797261, 2020). "A young woman of 43 years of age presented with hypercalcaemia (Ca 2.8 mmol/l, 11.2 mg/dl), normal PTH levels (4.4 pmol/l) and low CCCR of 0.31%." (PMID 31797261, 2020). "Laboratory results demonstrated hypercalcemia (13.2 mg/dL), depressed parathyroid hormone (PTH) (4.8 pg/mL), slightly elevated parathyroid hormone-related protein (PTHrp) (5.0 pmol), and elevated Vitamin D 1,25 OH (248 pg/mL)." (PMID 33403173, 2020). "On evaluation, both had hypertension, severe hypercalcemia (serum calcium 14.1 mg/dL and 14.5 mg/dL, respectively) and elevated parathyroid hormone levels." (PMID 32129057, 2020). "Primary hyperparathyroidism (PHPT) is a common endocrine disorder characterized by hypercalcemia and high or inappropriately normal parathyroid hormone (PTH) levels." (PMID 32118376, 2020). "Here, we show that mice lacking the transient receptor potential canonical channel 1 (TRPC1) develop chronic hypercalcemia, hypocalciuria, and elevated PTH levels, mimicking human FHH." (PMID 32213715, 2020). "The present review provides a clinical perspective of PTH-related hypercalcaemia, with a focus on the differentiation of the two contrasting benign conditions of PHPT and FHH." (PMID 31797261, 2020). "Primary hyperparathyroidism (PHPT) is characterized by hypercalcemia and abnormal excessive flow of PTH." (PMID 33015068, 2020).
Hypercalcemia (continued). "In 2005, her laboratory investigations detected hypercalcemia (3.35 mmol/L), hypercalciuria (22.56 mmol/d), and elevated serum PTH levels (561 pg/mL)." (PMID 33101196, 2020). "Serum levels of β‐CTX, tPINP, and osteocalcin (OC) were significantly elevated but PTH levels significantly decreased in patients with hypercalcemia." (PMID 33145966, 2020). "Laboratory examination showed hypercalcemia: 2.81 mmol/l (normal range: 2.08–2.71 mmol/l), hypophosphatemia: 0.66 mmol/l (normal range: 0.81–1.45 mmol/l), and a high PTH level: 916.0 pg/ml (normal range: 11.0–67.0 pg/ml)." (PMID 31931802, 2020). "PTH, hemoglobin, creatinine, and uric acid were the factors most closely related to hypercalcemia in multivariate analysis." (PMID 33145966, 2020). "Primary hyperparathyroidism (PHPT) is a common endocrine disorder that is characterized by hypercalcemia and elevated or inappropriately normal serum levels of parathyroid hormone." (PMID 31931802, 2020). "Her laboratory investigations revealed hypercalcemia (3.15 mmol/L, normal range: 2.13–2.70 mmol/L) and elevated serum PTH levels (2,136 pg/mL, normal range: 13–65 pg/mL)." (PMID 33101196, 2020). "Proteins encoded by the FHH-associated genes function in a linear signaling pathway within the PTG to suppress production and secretion of PTH in response to hypercalcemia." (PMID 32213715, 2020). "The use of cinacalcet for patients with PHPT in combination with anti-resorptive to control hypercalcemia and to improve skeletal health from elevated PTH level would warrant further investigations." (PMID 32621588, 2020). "Statistically, as a group, patients with FHH exhibit mild but significant hypercalcemia, while a few of them show elevated PTH, similar to male Trpc1–/– mice." (PMID 32213715, 2020). "The hypersecretion of parathyroid hormone (PTH) leads to persistent hypercalcemia and is clinically manifested as weakness in limbs, bone pain, recurrent urinary calculi, dry mouth, dyspepsia, and constipation." (PMID 32376878, 2020). "It is characterized by hypercalcemia sustained by inappropriate high parathyroid hormone (PTH) levels, the latter due to a parathyroid neoplasm." (PMID 32411220, 2020). "Cinacalcet treatment corrected hypercalcemia and decreased PTH levels in 10 kidney transplant recipients with hypercalcemia and severe PHPT, but re-elevated in two patients who discontinued cinacalcet." (PMID 32913586, 2020). "In contrast to PHPT, FHH is an inherited disorder with a strong family history, characterised by lifelong hypercalcaemia with normal (80% of patients) or mildly raised PTH levels and hypocalciuria." (PMID 31797261, 2020). "The signs and symptoms are a combination of the effects of increased PTH secretion as well as hypercalcemia." (PMID 32555278, 2020). "A woman in her seventies presented with hypercalcaemia (Ca = 3.00 mmol/l, 12.0 mg/dl) and hyperparathyroidism (PTH = 10.9 pmol/l), and her CCCR was elevated at 1.5%." (PMID 31797261, 2020). "A woman in her sixties presented with hypercalcaemia (Ca = 3.23 mmol/l, 12.9 mg/dl), hyperparathyroidism (PTH = 42.1 pmol/l) and a high CCCR (2.8%)." (PMID 31797261, 2020). "Multivariate analysis showed that serum PTH, hemoglobin, creatinine, and uric acid levels were the main factors affecting hypercalcemia." (PMID 33145966, 2020). "Compared to PHPT in adults, PHPT in children is reportedly more symptomatic, with a greater incidence of hypercalcemia and hypercalciuria at similar concentrations of i-PTH." (PMID 32572650, 2020). "Algorithms for diagnosis of PTH related hypercalcaemia require assessment of a 24-h urinary Ca and creatinine excretion to calculate the Ca/creatinine clearance ratio (CCCR), expressed as a percentage (%)." (PMID 31797261, 2020).
Hypercalcemia (continued). "As some authors suggest, in a patient with PHPT, severe hypercalcemia (>14 mg/dL), very high serum PTH levels (five times above the normal range), concomitant severe renal and skeletal manifestations, and palpable cervical mass should raise suspicion for PC." (PMID 33343947, 2020). "The clinical presentation of parathyroid carcinoma includes severe hypercalcemia, a palpable neck mass, an amino parathyroid hormone (PTH) ratio >1 as measured by the third/second PTH assay, and local invasion or regional metastasis." (PMID 32149123, 2020). "BMA is an investigation which is indispensable to establish the etiology for PTH-independent hypercalcemia, and must be performed before starting corticosteroids to avoid missing the diagnosis of ALL." (PMID 32538178, 2020). "Considering the presence of hypercalcemia and elevated PTH serum level, with US and SPECT/CT evidence of pathological gland, a preoperative diagnosis of tertiary hyperparathyroidism was made." (PMID 33343947, 2020). "This is supported by abnormally high levels of Vitamin D 1,25 OH, moderate hypercalcemia, and low PTH." (PMID 33403173, 2020). "Initial laboratory evaluation revealed hypercalcemia (serum calcium 3.69 mmol/L, RR 2.0–2.6 mmol/L), hypophosphatemia (serum phosphorus 0.40 mmol/L, RR 0.67–1.04 mmol/L), and hyperparathyroidism (PTH 284.0 pg/mL, RR 15–68.3 pg/mL)." (PMID 32871939, 2020). "Algorithms for diagnosis of PTH related hypercalcaemia require assessment of a 24-h urinary calcium and creatinine excretion to calculate calcium/creatinine clearance ratio and radiological investigations including ultrasound scan and 99mTc-sestamibi-SPECT/CT." (PMID 31797261, 2020). "Fifteen were undergoing routine investigations for PTH-related hypercalcaemia at The Royal Free Hospital, University College London: the remainder were healthy participants who served as a control set." (PMID 31797261, 2020). "Other methods to induce osteogenesis, such as PTH therapies, bisphosphonates, and Romosozumab have been implemented, but they also pose side-effects, such as tumor growth, hypercalcemia, and jaw osteonecrosis." (PMID 32933207, 2020). "Both patients had mild hypercalcemia, relatively low urinary calcium excretion, elevated calcitriol, and low-to-normal intact PTH." (PMID 33062349, 2020). "Primary hyperparathyroidism (PHPT) is biochemically confirmed by hypercalcemia and inappropriately increased concentrations of parathyroid hormone (PTH)." (PMID 33207657, 2020). "Work-up for hypercalcemia was: Parathyroid hormone (PTH)-6.2 pg/mL, 25 -hydroxy vitamin D-10 ng/mL and 1, 25-dihydroxy vitamin D (calcitriol)- 15 ng/mL." (PMID 32538178, 2020). "Antitubercular treatment allowed correction of hypercalcemia; frank hyperparathyroidism (PTH 400–800 pg/mL) became evident and the patient is now scheduled for adenomectomy." (PMID 32075103, 2020). "In primary hyperparathyroidism often resulting from PTG adenomas, abnormally high levels of PTH result in hypercalcemia, whereas in secondary hyperparathyroidism, frequently seen in renal failure, elevated PTH levels are actually associated with hypocalcemia." (PMID 32213715, 2020). "Four patients had primary hyperparathyroidism with elevated levels of PTH and persistent hypercalcemia (albumin corrected or ionized calcium)." (PMID 31950464, 2020). "Primary hyperparathyroidism is an endocrine disorder characterized by hypercalcemia and elevated or inappropriately normal levels of parathyroid hormone." (PMID 33348402, 2020). "In the early post-transplant period, pre-transplant hyperparathyroidism contributes to inappropriate hypercalcemia and/or hypophosphatemia in the presence of improved kidney responsiveness to PTH." (PMID 32792668, 2020). "Reduced PTH secretion in the neonatal period can arise from delayed parathyroid gland maturation, hypomagnesemia, or as a consequence of maternal hypercalcemia, which suppresses fetal parathyroid activity." (PMID 32150253, 2020).